GPR139 (G protein-coupled receptor 139)
Description:
Orphan receptor. Seems to act through a G(q/11)-mediated pathway.
Synonyms: GPRG1; PGR3
Tractability: Small molecule: a structure with a bound ligand is known; a high-quality ligand is known; it belongs to a druggable protein family. Antibody: UniProt places it where antibodies can reach, with medium confidence; UniProt predicts a signal peptide or a membrane-spanning region; its Gene Ontology location is reachable by antibodies, with medium confidence. PROTAC: a small molecule that binds it is known.
Target class: Family A G protein-coupled receptor; Membrane receptor
Gene: Protein-coding gene on chromosome 16 (20,028,239 to 20,073,890, reverse strand). Ensembl gene ENSG00000180269.
Subcellular location: Cell membrane
Gene Ontology:
Molecular function: G protein-coupled receptor activity; identical protein binding; neuropeptide receptor activity
Biological process: G protein-coupled receptor signaling pathway; phospholipase C-activating G protein-coupled receptor signaling pathway; neuropeptide signaling pathway
Cellular component: membrane; plasma membrane
Genetic constraint (gnomAD): Loss-of-function variants: 12 observed, 26.71 expected, observed/expected ratio (o/e) 0.45, 90% interval 0.29 to 0.73. The upper end of that interval is the gene's LOEUF score, 0.73, which puts it in group 2 of 6, group 1 being the genes least tolerant of losing a copy. Missense variants: 378 observed, 469.45 expected, observed/expected ratio (o/e) 0.81, 90% interval 0.74 to 0.88. Synonymous variants: 182 observed, 186.91 expected, observed/expected ratio (o/e) 0.97, 90% interval 0.86 to 1.1.
Homologues: Orthologues: chimpanzee GPR139 (100% identical), macaque GPR139 (100% identical), dog GPR139 (99% identical), guinea pig GPR139 (97% identical), mouse Gpr139 (94% identical), pig GPR139 (94% identical), rat Gpr139 (94% identical), tropical clawed frog gpr139 (88% identical), rabbit GPR139 (88% identical), zebrafish GPR139 (73% identical), Drosophila melanogaster FMRFaR (26% identical), Drosophila melanogaster CNMaR (22% identical), and 133 more. Paralogues in human: GPR142 (38% identical).
Diseases named in the same sentence as GPR139 in open-access papers:
GPR139 is named in the same sentence as 29 diseases in open-access papers, as found by Europe PMC text mining. Sharing a sentence is not in itself a finding about the gene and the disease. The quoted sentences say what the papers report.
schizophrenia (9 papers, 2019 to 2025). A major psychotic disorder characterized by abnormalities in the perception or expression of reality. "Genetic variations in the GPR139 locus have been linked to symptoms of inattention in attention-deficit hyperactivity disorder and schizophrenia." (PMID 39717703, 2024). "GPR139 agonism is a novel candidate mechanism for the treatment of schizophrenia and other disorders associated with social and cognitive dysfunction." (PMID 34675381, 2022). "Another study using mouse models demonstrated the possible involvement of GPR139 signaling in the neuropsychiatric process with schizophrenia-like pathology." (PMID 39717703, 2024). "The behavioral anomalies seen upon loss of GPR139 in mice, including hyperactivity and PPI deficits, are reminiscent of schizophrenia symptoms in humans." (PMID 39717703, 2024). "The role of GPR139 in the brain has been elucidated mainly in mice models with implications in neuropsychiatric diseases such as opioid addiction and schizophrenia." (PMID 39717703, 2024). "GPR139 has been proposed to have a role as a therapeutic target in schizophrenia, addiction and metabolic disorders, and attention-deficit/hyperactivity disorder, as well as Parkinson’s disease and phenylketonuria." (PMID 34675381, 2022). "GPR139 has been shown to inhibit D2 receptor-dependent signaling and in fact, treatment with the D2 receptor antagonist haloperidol in GPR139 KO mice ameliorated several of the schizophrenia-related behavioral deficits." (PMID 36051635, 2022). "Notably, a phase I clinical study of the potent and selective GPR139 agonist TAK-041 demonstrated good tolerance in both healthy volunteers and patients with stable schizophrenia." (PMID 35990593, 2022). "Respectively, a mouse model of altered DA-ergic signaling lacking the orphan receptor GPR139 exhibited schizophrenia-like features such as deficits in sensorimotor integration, social behavior, object and conspecific recognition, together with impairments in an FR5 operant conditioning task." (PMID 36051635, 2022). "Another GPR139 agonist 4-oxo-3,4-dihydro-1,2,3-benzotriazine has been reported to improve social withdrawal in a preclinical model of the negative symptom of schizophrenia, involving the mesocortical pathway (initiate from VTA but instead project to the prefrontal cortex)." (PMID 30971885, 2019).
Parkinson disease (6 papers, 2016 to 2025). A progressive degenerative disorder of the central nervous system characterized by loss of dopamine producing neurons in the substantia nigra and the presence of Lewy bodies in the substantia nigra and locus coeruleus. "The role of GPR139 in neurodegenerative diseases such as Parkinson’s disease (PD) and AD has been examined using different experimental models." (PMID 40102345, 2025). "It has therefore been suggested that GPR139 is a possible target for metabolic disorders and Parkinson’s disease." (PMID 28442765, 2017). "Our results support differential mechanisms of toxicity for those substances commonly used in Parkinson’s disease (PD) models and potential for GPR139 agonists in neuroprotection." (PMID 27445691, 2016). "Based on these findings, GPR139 has been hypothesized as a potential target for the treatment of diseases with impaired movement control, e.g. Parkinson’s disease." (PMID 28442765, 2017).
Alcohol (2 papers, 2018 to 2021). "Because of the high expression of GPR139 in the habenula, a critical brain region in addiction, we hypothesized that GPR139 may play role in alcohol dependence." (PMID 29971251, 2018).
alcohol use disorder (2 papers, 2018 to 2025). "GPR139 risk variants (rs72771074 and rs2764771) have been found to be associated with alcohol use disorder in two independent populations, thus demonstrating that GPR139 has a physiological role in the neurocircuitries of reward and addiction." (PMID 40102345, 2025). "GPR139 risk variants were also found to be associated with alcohol use disorder in two independent studies." (PMID 40102345, 2025). "JNJ-63533054 reportedly rescued addiction-like behaviors in alcohol-dependent rats, suggesting that GPR139 may be a potential therapeutic target for alcohol use disorder." (PMID 40102345, 2025). "In my opinion the work is novel and has important implications suggesting that GPR139 may be a novel target for the treatment of alcohol use disorder." (PMID 29971251, 2018). "In this sense, GPR139 might be a novel target for the treatment of alcohol use disorder." (PMID 29971251, 2018).
Anxiety (2 papers, 2019 to 2025). Intense feelings of nervousness, tension, or panic often arise in response to interpersonal stresses. "To further explore the therapeutic potential of the GPR139 agonists, we evaluated in vivo activity of the potent scaffold in mice in the open-field test to assess locomotion and anxiety." (PMID 41365886, 2025). "Given this, it would be interesting to test the GPR139 agonist in models of mood and anxiety that have a more chronic component in lieu of the acute or sub-chronic models used here, such as the chronic mild stress model." (PMID 30949055, 2019). "In the classical tests of anxiety, the GPR139 agonist produced a small decrease in the number of marbles buried, but this possible anxiolytic-like effect did not extend to the EPM." (PMID 30949055, 2019). "Thus, GPR139 appears expressed in an interconnected circuit involved in mood, motivation, and anxiety." (PMID 30949055, 2019).
alcohol addiction (1 paper, 2018). "The authors have conducted a set of experiments examining the role of the orphan receptor GPR139 in alcohol addiction and withdrawal." (PMID 29971251, 2018). "In this manuscript, the authors report on studies examining if the modulation of GPR139 may be relevant to alcohol addiction-related behaviors." (PMID 29971251, 2018). "Given the high expression of GPR139 in the habenula, we hypothesized that the modulation of GPR139 may be relevant to alcohol addiction-related behaviors." (PMID 29971251, 2018).
Arthritis (1 paper, 2024). Inflammation of a joint. "GPR139 is present mainly in the central nervous system but GPR142 is highly expressed on immune cells and it was found that its receptor antagonist CLP-3094 alleviated collagen antibody-induced arthritis in mice." (PMID 38612652, 2024).
behavioral disorders (1 paper, 2025). "This review aims to facilitate future studies in contextual analyses and experimental designs, contributing to the understanding of GPR139 as a therapeutic target for neuropsychiatric and behavioral disorders." (PMID 40102345, 2025). "Here, we highlight current in vitro and in vivo studies of GPR139, its potential physiological roles, and therapeutic potential in the pathophysiology of neuropsychiatric and behavioral disorders." (PMID 40102345, 2025). "Here, we review the current knowledge on GPR139 and explore the potential physiological roles of GPR139 in the context of neuropsychiatric and behavioral disorders." (PMID 40102345, 2025). "This review aims to focus on the current knowledge gaps to facilitate future studies that will contribute to the understanding of GPR139 as a therapeutic target for neuropsychiatric and behavioral disorders." (PMID 40102345, 2025). "However, like many other GPCRs, the physiological role of GPR139 in the pathophysiology of neuropsychiatric and behavioral disorders remains relatively elusive, as current studies are considered preliminary and not currently validated in humans or other vertebrate phylogenetic taxa." (PMID 40102345, 2025).
breast adenocarcinoma (1 paper, 2022). "Comparative analysis across TCGA pan-cancer gene-expression data confirmed GPR139 was highly expressed in subsets of PCPG, while also in CNS malignancies and a subset of breast adenocarcinomas." (PMID 36271074, 2022).
cognitive deficits (1 paper, 2025). "Evidence from both animal studies and human genetic association studies has demonstrated that dysregulation of GPR139 expression and function is linked to aberrant behaviors, cognitive deficits, alterations in sleep and alertness, and substance abuse and withdrawal." (PMID 40102345, 2025).
diabetes (1 paper, 2017). "Since the GPR139 receptor shares the same ligands and is expressed in the hypothalamus it is possible that GPR139 is also involved in the pathophysiology of diabetes." (PMID 28442765, 2017). "Taken together GPR139 has been hypothesized as a potential target for the treatment of the metabolic syndrome e.g. diabetes and eating disorders." (PMID 28442765, 2017).
insomnia (1 paper, 2025). A sleep disorder characterized by difficulty in falling asleep and/or remaining asleep. "Multiple SNPs have been reported at the GPR139 loci for insomnia." (PMID 40102345, 2025).
memory impairment (1 paper, 2021). "Thus, it is possible that GPR139 signalling could play a role in opioid-sensitivity and its associated memory impairment to some extent." (PMID 33692406, 2021).
mental disorder (1 paper, 2018). A disease that has its basis in the disruption of mental process. "The modulation of GPR139 receptor function has been hypothesized to be beneficial in the treatment of some mental disorders, but behavioral studies have not yet provided causal evidence of the role of GPR139 in brain dysfunction." (PMID 29971251, 2018).
neuroblastoma (1 paper, 2016). Neuroblastoma (NB) is the most common solid, extracranial childhood tumor. "Gpr139 expression was about two orders of magnitude higher in primary midbrain cultures, compared to expression in a mouse fibroblast cell line, or a neuroblastoma cell line." (PMID 27445691, 2016).
substance dependence (1 paper, 2022). The psychological or physiological need to take a substance in order to experience its effects or to avoid the effects of its absence. "Studies using GRP139 agonists or antagonists suggest that GPR139 signaling contributes to substance dependence in animal models." (PMID 35990593, 2022).
type II diabetes (1 paper, 2021). "Thus, GPR139 could be a potential target for treating metabolism-related disorders such as obesity and type II diabetes." (PMID 34943862, 2021).
withdrawal syndrome (1 paper, 2025). "GPR139 agonism may act as a preventive therapeutic avenue for regulating withdrawal syndrome and addiction symptoms through its ability to inhibit MORs via the activation of Gq/11 and the recruitment of β-arrestin to MORs." (PMID 40102345, 2025).
cancer (2 papers, 2020 to 2022). A tumor composed of atypical neoplastic, often pleomorphic cells that invade other tissues. "This suggests the possible role of novel GPR139 and GPR142 as the substances for initiating a physiological response to handle the condition incurred as a result of cancer." (PMID 33679382, 2020).
neurodegenerative disease (2 papers, 2024 to 2025). A disorder of the central nervous system characterized by gradual and progressive loss of neural tissue and neurologic function. "Findings from these two independent studies suggest that GPR139 plays a neuroprotective role in neurodegenerative diseases and that its use as a preventive treatment against neuronal damage is due to its selective binding to GPR139." (PMID 40102345, 2025). "This study revealed that GPR139 is a promising treatment target for neurodegenerative diseases; however, the effects of JNJ-63533054 in human subjects have not been validated through clinical trials." (PMID 40102345, 2025). "Although GPR139 is less studied compared to other GPCRs, recent research has revealed its significant role in various neurodegenerative diseases, such as schizophrenia and AD." (PMID 39451571, 2024). "The combination of GPR139′s involvement in neuroprotective signaling and its ligand flexibility makes it an exciting candidate for therapeutic interventions in neurodegenerative diseases and opioid use disorders." (PMID 39451571, 2024).
tumor (1 paper, 2020). "The current work initially analyzes GPR139 and GPR142 for its genomic alteration via tumor samples." (PMID 33679382, 2020).
GPR139 also shares sentences with these, for which no sentence is quoted: attention deficit-hyperactivity disorder (3 papers); metabolic disorders (2); cervicitis (1); drug dependence (1); major depressive disorder (1); phenylketonuria (1); squamous intraepithelial lesions (1); substance abuse (1).